INS (insulin)
Diseases named in the same sentence as INS in open-access papers (continued):
Sharing a sentence is not in itself a finding about the gene and the disease.
Obesity (continued). "Total SOD activity was negatively correlated with parameters elevated in obesity: TChol, TG, CRP, insulin concentration, BMI, and HOMA-IR indices." (PMID 32709094, 2020). "During obesity and aging, cells of the innate and adaptive systems accumulate inside the VAT where they alter the local inflammatory environment and impact insulin sensitivity." (PMID 32499756, 2020). "For example, leptin and insulin interact with hypothalamic neuropeptides NPY, MCH, and α-MSH, not only regulating appetite, but also activating the SNS, possibly contributing to obesity-related hypertension." (PMID 33644105, 2020). "Excessive PTP1B activities impairs insulin sensitivity and signal transduction, thus participates in T2DM and regulate energy in brain mediating leptin receptors and contribute to obesity." (PMID 32998300, 2020). "As UCPs affect the process of insulin secretion in response to actual glycemia, maintaining proper SOD2 activity is important in context of obesity." (PMID 32709094, 2020). "The potential underlying mechanism of Erchen decoction for the treatment of obesity, hyperlipidemia and fatty liver is to increase the CDKAL1 production, improve islet cell function and insulin level." (PMID 32477116, 2020). "Obesity is a pathophysiological condition where excess free fatty acids (FFA) target and promote the dysfunctioning of insulin sensitive tissues and of pancreatic β cells." (PMID 32668665, 2020). "Our study goal was to investigate whether a mouse model of VFHD-induced obesity can be used for evaluating the versatile protective effects of curcumin against a set of manifestations of obesity, which are often investigated separately: insulin resistance, liver pathophysiology, and osteoarthritis." (PMID 32992936, 2020). "These knockout (KO) mice on the same high-fat diet were also resistant to developing obesity, because of reduced adiposity, likely due to the JNK effect on hypothalamic inflammation affecting central regulation of energy balance by insulin and leptin." (PMID 32183037, 2020). "With specific reference to obesity, studies in mice models highlighted the abundant presence of P2Y14R mRNA in the pancreas and its implication in the modulation of insulin secretion." (PMID 32793208, 2020). "In contrast to metabolically unhealthy obesity (MUO), the MHO phenotype has a favorable lipid profile and a normal or only slightly affected insulin sensitivity, despite the similar amount of body fat." (PMID 32386512, 2020). "The majority of people with obesity, T2DM and CKD were treated with medications that promote weight gain, including sulphonylureas and insulin; GLP1RAs and SGLT2is were infrequently prescribed in this setting." (PMID 32845571, 2020). "As expected, we found that participants with severe obesity (BMI ≥ 35 kg/m2) and NFG, IFG, or T2DM, had significantly lower (S(I) but higher insulin secretion (Φ) compared with normal weight participants who had NFG." (PMID 31720686, 2020). "In animal models of obesity, RSV, by increasing basic metabolic rate and insulin sensitivity, has been found to successfully counteract the effects of a high-fat diet and to prevent ovariectomy-associated weight gain." (PMID 32102233, 2020). "Another family of inflammatory molecules c-Jun N-terminal kinases (JNKs) are activated in obesity; when JNK1 KO mice were fed HFD they gained less weight, had smaller adipocytes, and improved insulin sensitivity compared to wildtypes." (PMID 33240218, 2020). "In conclusion, the findings of this study revealed a higher concentration of insulin and HOMA-IR index in individuals with normal weight obesity compared to women with both normal weight and normal fat mass as a control group." (PMID 33198735, 2020). "In the setting of obesity, we found that IGFBP-1 enhanced whole-body glucose tolerance and insulin sensitivity through interaction of its RGD domain with cell surface integrin receptors." (PMID 32190801, 2020).
Obesity (continued). "Long term intake of high protein diet in obesity-prone rats reduced food intake and WAT mass while improving basal blood sugar, insulin levels, leptin, and triglyceride levels in addition to glucose tolerance." (PMID 33282920, 2020). "This is one reason why during obesity there is elevated free fatty acids (FFA) in plasma, although the main driver of the enhanced adipose tissue lipolysis is insulin resistance." (PMID 32183037, 2020). "Conventional treatments for obesity and diabetes, including metformin, GLP1 receptor agonists, and TZDs, lead to improvements in insulin sensitivity while also providing anti-inflammatory benefits." (PMID 32408016, 2020). "Increasing insulin sensitivity represents a therapeutic strategy for prevention and treatment of T2DM, obesity, and metabolic syndrome." (PMID 32280711, 2020). "Obesity and PEM also alter metabolic parameters that can influence DENV infection: for example, glucose, insulin, lipids, micronutrients, and many more factors." (PMID 32854687, 2020). "Obesity and T2D in human and mice can activate FTO in the brain tissues by defective insulin signaling." (PMID 32982666, 2020). "Depression frequently co-occurs with disorders of glucose and insulin homeostasis (DGIH) and obesity." (PMID 30854996, 2020). "Direct molecular disruption of DVC ERK1/2 signaling in normal rats induces hyperphagia and obesity, whereas daily acute repeated DVC insulin infusion lowers food intake and body weight in normal rats." (PMID 32872540, 2020). "In addition to the deleterious effects on hepatic physiological processes, TMEM16A also exerted systemic effects including obesity, adipocyte hypertrophy, visceral fat weight gain, glucose intolerance, and insulin hyposensitivity, which may be attributed primarily to liver dysfunction." (PMID 32440483, 2020). "PWS exhibited lower muscle mass (p < 0.001), FFM (p < 0.001), REE (p < 0.001), as well as insulin (p < 0.05), HOMA-IR (p < 0.05) and triglycerides levels (p < 0.05) than controls with common obesity." (PMID 31974460, 2020). "One of the most-used models of obesity is that of diet-induced obesity (DIO), which—within a few weeks—produces metabolic abnormalities such as insulin resistance and lipid accumulation intracellular lipid droplets in the liver." (PMID 32698439, 2020). "The multidisciplinary medical management of obesity can be difficult in T2DM due to potential weight gain from medications including sulphonylureas and insulin." (PMID 32832564, 2020). "Although how obesity contributes to the mitochondrial dysfunction is still not clear, it is postulated that the induced inflammation and metabolic alteration implicated by impaired insulin function could be a possible factor." (PMID 32455946, 2020). "The downregulation of stearoyl-coenzyme A desaturase-1 (SCD1), and the enhancement of insulin and leptin sensitivity have been suggested as a curative measures in HFD-induced obesity." (PMID 32260306, 2020). "Leptin crosstalks with various molecular mediators of the obesity such as VEGF, estrogen, IGF-1, insulin and inflammatory cytokines." (PMID 33511131, 2020). "Thus, we speculate that simultaneously increased plasma levels of free fatty acid, TNF-α and MIP-1α/CCL3 may have the potential to induce significant pathophysiological changes in the adipose tissue compartment in obesity, including changes in insulin sensitivity and lipid metabolism." (PMID 33050324, 2020). "BMI, WC, lipid profile, glucose, insulin and HOMA were used as surrogates of obesity and MeS indicators in the current study." (PMID 32708841, 2020). "Obesity, often present in GDM, also increases the need for insulin therapy during pregnancy and increases women’s vulnerability to T2DM after childbirth." (PMID 33333828, 2020). "Obesity and a high fat diet (HFD) can induce insulin resistance, which, subsequently, impairs insulin signaling in the periphery as well as in the brain." (PMID 32455946, 2020).
Obesity (continued). "In the obesity-cancer relationship, multiple biological processes including insulin, insulin-like growth factor (IGF)-1, insulin resistance, sexual hormones (estrogens) and pro-inflammatory cytokines (TNF-α, IL-6 and CRP) actively participate." (PMID 32811441, 2020). "This feed forward effect increases obesity-induced circulating FFA concentration, leading to insulin resistance." (PMID 32922298, 2020). "Our results showed that the administration of scopolin decreased serum levels of insulin and leptin, indicating the inhibition of OVX-induced obesity by preventing insulin/leptin resistance." (PMID 33218042, 2020). "From our study, we suggest that pre-treatment obesity itself is not the cause of cancer-associated sequelae, but the adiposity-related metabolic abnormalities include pro-inflammatory macrophage polarisation, insulin resistance, and disproportionate adipokine secretion by adipose tissue." (PMID 32512860, 2020). "The C57BL/6J mice (n = 6 per group) fed with high fat diet (HFD) for 16 weeks presented anticipated features of NASH with obesity, elevated ALT and insulin resistance compared to mice fed standard diet (SD)." (PMID 33199780, 2020). "Multiple molecular alterations, including insulin resistance, IGF pathway and inflammatory cytokines hyperactivation, are involved in obesity, which is able to modulate the biological behavior of BC cells and tumor microenvironment." (PMID 32391265, 2020). "The impaired levels of insulin, HOMA-IR, TG, HDL-C, and total- and HMW-adiponectin in the obese group compared to the normal group confirm the remarkable impact of obesity on metabolic disorders." (PMID 31552725, 2020). "Adipocyte specific ATG7 k/o mice are lean with reduced fat mass, increased insulin sensitivity, an increase in BAT thermogenesis and are resistant to diet-induced obesity." (PMID 32265830, 2020). "In the liver, EPO inhibited gluconeogenesis, attenuated obesity-related inflammatory cytokine expression and production of TNF-α and IL-6, reduced the activation of NFκB and inflammatory signaling, and enhanced insulin-related PI3K signaling." (PMID 33330462, 2020). "In an HFD model of obesity, A1AR KO mice were heavier than WT mice, had elevated fasting plasma and insulin levels and had impaired glucose clearance, as determined in hyperinsulinemic-euglycemic clamp studies." (PMID 33050467, 2020). "We also found that the administration of phloretin significantly inhibited the serum levels of leptin, glucose, and insulin and increased serum adiponectin levels compared to mice with HFD-induced obesity." (PMID 33014333, 2020). "It has been conclusively demonstrated that obesity triggers NLRP3 activation and that secreted IL-1β that impairs insulin signaling, which contributes to IR in mice." (PMID 33519369, 2020). "Hyperinsulinemia is a marker of obesity and reduced SWS has been shown to influence insulin insensitivity in young adults." (PMID 33171633, 2020). "The NLRP3 inflammasome impairs insulin sensitivity in dietary-induced obesity via the disruption of phosphatidylinositol 3-kinase-protein kinase B (PI3K-Akt) signaling, a major pathway orchestrating the metabolic effects of insulin in peripheral tissue." (PMID 32545355, 2020). "Diastolic BP, heart rate, and circulating levels of insulin, triglyceride, and hs-CRP were higher, but percentage skeletal muscle and HDL-cholesterol levels were lower in the obesity group than the normal-weight and overweight group." (PMID 33375318, 2020). "Because the sympathoexcitatory response to insulin depends on α-MSH in the PVN, this result indirectly suggests that insulin’s activation of ArcN POMC neurons is also weakened with obesity in females." (PMID 32160920, 2020). "We aimed to investigate the impact of obesity in youth on later pancreatic intrinsic nervous system (PINS) phenotype and control of insulin secretion." (PMID 31922022, 2020).
Obesity (continued). "Diet induced obesity also results from gliosis which makes both POMC and AgRP neurons insensitive to the peripheral insulin." (PMID 31143098, 2019). "However, the mechanism by which this occurs—and specifically the possible role of alterations in systemic glucose metabolism and potential ability of changes in plasma insulin concentrations to mediate differences in tumor glucose metabolism—has not been explored in obesity-associated tumor types." (PMID 31867105, 2019). "Increased endogenous acetate production (Ra) in rodents has been shown to activate the parasympathetic nervous system and thereby promote increased glucose-stimulated insulin secretion (GSIS), increased ghrelin secretion, hyperphagia and obesity." (PMID 31404159, 2019). "Pharmacological JNK inhibition (with SP600125), markedly improved insulin-mediated vasodilation and vascular endothelial function, further suggesting JNK as a potential target in obesity-related vascular diseases." (PMID 31270248, 2019). "We found strong negative associations for adiponectin levels with BMI, WHR, LDL cholesterol, total cholesterol, triglycerides, fasting glucose, fasting insulin, and HOMA-IR, as well as dyslipidemia, overweight and obesity status." (PMID 30816311, 2019). "An increase in the levels of the negative regulators of insulin signaling in the hypothalamus such as TCPTP, PTP1B, and SOCS3 also have been shown and these factors also increase as a result of obesity induced inflammation." (PMID 31143098, 2019). "Their metabolic parameters (glucose and insulin levels; total, HDL and LDL cholesterol, triglycerides) were normal; their BMI was in the obesity range." (PMID 31108989, 2019). "Male mice with global deletion of the renin gene are lean due to enhanced energy expenditure, have improved insulin sensitivity, and are resistant to development of HFD-induced obesity." (PMID 31262355, 2019). "Definition of IR in T2DM means “reduced sensitivity in body tissues to the action of insulin,” ordinarily observed in T2DM and obesity, characterized as hyperinsulinemia and dyslipidemia." (PMID 31969813, 2019). "Mice with obesity induced by monosodium glutamate (MSG mice) develop increased tau hyperphosphorylation due to central insulin resistance manifested by decreased activation of the insulin signaling cascade." (PMID 31653061, 2019). "According to previous studies, insulin regulates synaptic plasticity in the hippocampus, and HFD-induced obesity reduces hippocampal BDNF levels and neurogenesis, and this leads to impairments in cognitive function." (PMID 31311133, 2019). "In terms of obesity and the sphere of weight management, RSV has demonstrated significant improvement of glucose control and insulin sensitivity in diabetics." (PMID 30641865, 2019). "A total of 10 studies analyzed fasting insulin for whole subjects, including 5 studies for T2DM and 5 for simple obesity." (PMID 31760943, 2019). "When compared by BMI groups, gamma-linoleic acid (18:3n6) was negatively correlated with insulin (β = -3.59, R2 = 0.50, p<0.05) and positively correlated with TNF-α (β = 0.60, R2 = 0.39, p<0.05) among women with overweight and obesity only." (PMID 31141526, 2019). "Changes in miR-155 in obese mice can induce obesity and non-alcoholic fatty liver disease (NAFLD) and led to an increase in resistin, which regulates insulin sensitivity." (PMID 31207998, 2019). "As whole-body deletion of PTP1B was proven to be beneficial in improving global insulin sensitivity, glucose homeostasis and conferred resistance to HFD-induced obesity, the tissue responsible for PTP1B effects remained questionable." (PMID 31319588, 2019). "The similarity of insulin signalling defects in uraemic and obese milieus raises the question as to why skeletal muscle wasting seems more prominent in CKD than in obesity." (PMID 31195596, 2019).
Obesity (continued). "The high glycemic index associated with the Western dietary pattern results in a rapid increase in insulin and postprandial serum glucose levels and contributes to the induction of liver lipogenesis and VDRL secretion, which can result in obesity." (PMID 31779112, 2019). "C1ql3 is expressed in β-cells, its expression is elevated in islets obtained from mouse models of obesity (HFD-induction, Ob/Ob, and Db/Db), and it inhibits insulin secretion from mouse islets and INS1(832/13) β-cells." (PMID 31300714, 2019). "In patients with obesity, several biochemical parameters are altered including FFA, TG, cholesterol, vitamin D, insulin, and leptin." (PMID 31207920, 2019). "Insulin and IGF signaling combined with chronic inflammation are also important factors in the CRC-promoting effects of obesity." (PMID 31623387, 2019). "While participants with obesity achieved higher plasma sucralose concentrations than normal-weight participants 4–5 h post-sucralose ingestion, it is unlikely that such difference could explain the divergent insulin responses between weight groups observed 1 h post-sucralose ingestion." (PMID 31877631, 2019). "In Lkb1 single KO Adipoq-Lkb1 mice, the improved systemic insulin sensitivity and energy expenditure result in resistance to HFD-induced obesity." (PMID 30318987, 2019). "Ruiz-Ojeda in the 1,020 review draws the following conclusions: obesity reported that associations with VDR polymorphisms could be related to either a direct effect of vitamin D in adipocyte differentiation and metabolism, or an indirect effect by modulation of insulin secretion." (PMID 30881343, 2019). "Other studies have also shown that the prevalence of overweight and obesity in T1DM has increased over the last years, mainly due to intensive insulin treatment and changes in diet." (PMID 30617710, 2019). "Interestingly, several miRNAs have recently been found to regulate adipose tissue biology (development and metabolism), insulin secretion and action, and therefore their imbalance may play a role in the development of obesity and related metabolic complications." (PMID 31404962, 2019). "In particular, consistent data from literature have pointed out a clear relationship between obesity and nonalcoholic fatty liver disease (NAFLD) being insulin resistant is a main driven factor." (PMID 31906216, 2019). "For example, Inositol Polyphosphate Phosphatase-Like 1 (Inppl1) knock out mice display insulin hypersensitivity, increased levels of phosphorylated AKT, and protection against diet-induced obesity." (PMID 31262088, 2019). "Anti-obesity effects of Th2s were indicated by CD4+ T cell transfer into Rag1−/− diet-induced obese (DIO) mice, which prevented weight gain and improved insulin sensitivity as a likely outcome of increased (STAT6-dependent) Th2s." (PMID 31379820, 2019). "Several cohort studies have found associations between inter-individual genetic variations in the INS/IGF-II/H19 locus and body weight and obesity as well as with abdominal and visceral fat." (PMID 31590432, 2019). "Interestingly, several miRNAs such as miR-9, miR-181a, and miR-132, are capable of regulating insulin pathways through sirtuin 1 (SIRT1), a nicotinamide adenosine dinucleotide (NAD) that regulates energy homeostasis, inflammation, and metabolic disease associated with obesity." (PMID 31817583, 2019). "Insulin signaling and PI3K-Akt signaling pathways are another major pathways which influence obesity or related syndrome." (PMID 31013288, 2019). "Depleting macrophages and B cells at obesity onset was sufficient to mitigate CD8+ T cell inflammation, while CD4+ T cell inflammation was rather subject to regulation by the adipocyte secreted insulin sensitizer adiponectin." (PMID 31736971, 2019).